FAT1 (FAT atypical cadherin 1)
Diseases named in the same sentence as FAT1 in open-access papers (continued):
Sharing a sentence is not in itself a finding about the gene and the disease.
cancer (continued). "After knockdown of FAT1, cancer cells became more sensitive to TRAIL-induced apoptosis, a process very similar to those: by interacting with FAT1, DRs finally prevent DISC activation." (PMID 33257838, 2021). "Judging from the frequency of somatic genetic alterations in YAP/TAZ and FAT1, the dependence on YAP/TAZ hyperactivation is likely to be greater in carcinomas originating from stratified squamous epithelia than other cancer types." (PMID 32859951, 2020). "Researchers also suggested that FAT1 inhibited migration and invasion in OSCC and some other types cancers." (PMID 31141819, 2019). "There were several established cancer genes involved in a total of 12 common CNAs identified according to GISTIC, including EGFR, CCND1, FHIT, and FAT1." (PMID 31159251, 2019). "Two gain regions contained the well-known oncogenes EGFR (7p11.2) and CCND1 (11q13.3) and several known cancer suppressor genes, such as FHIT (3p14.2–p12.1), FAT1 (4q35.1), CDKN2A (9p21.3), and ATM (11q22.3–q24.3), reside within the 10 deletion regions." (PMID 31159251, 2019). "Considering that FAT1 is overexpressed in both KRAS+ and KRAS− CRCs, these data support the development of anti-CRC cancer vaccines in which the D8-FAT1 epitope is used in combination with other CRC-specific antigens, including mutation-derived neoepitopes." (PMID 30416985, 2018). "Two cancers (#615 and #3008) had acquired homozygous deletions at the CDKN2A locus (chr9p21.3), and other homozygous deletions present in single cancers involved genes such as PPARGC1A, RFX3 and FAT1." (PMID 24777035, 2014). "The functional association between FAT1 and TGF-β1/TGF-β2 cytokines and the association of FAT1 with IL-10 cytokine and PD-L1/L2 immune checkpoints have not been reported in cancers so far." (PMID 35720420, 2022). "Hence, the positive correlation between the expression of FAT1 and TGF-β1/TGF-β2 extends to other cancers as well, in addition to GBM tumors." (PMID 35720420, 2022). "The following most altered cancer genes were LRP1B (26%), PIK3CA (24%), CDKN2A (24%), PTPRD (15%), RB1 (13%), PDE4DIP (13%), PCLO (11%), KRAS (11%), FAT1 (10%), and RELN (10%), and these results partially overlap with the most altered genes depicted in the experimental cohort." (PMID 35330454, 2022). "The roles of FAT1 in cancer progression, which seems to be cancer-type specific, have not been clarified." (PMID 35965328, 2022). "Mutations in MAATP53, EGFR, FAT4, KMT2C, ARID1A, FAT1, and RNF213 were observed in the original cancer tissues, whereas KRAS and BRAF mutations were not identified." (PMID 35721089, 2022). "Hence, our findings elaborate contributions of FAT1 to immune evasion, where FAT1 enables an immunosuppressive microenvironment in GBM and other cancers via TGF-β1/2." (PMID 35720420, 2022). "Compared to Del-c1 and c3, the majority of cancer genes were deleted by DEL-c2, such as CDKN2A (207/528), FHIT (133/528), KDM6A (42/528), RB1 (27/528), FAT1 (23/528), NFE2L2 (13/528), ERBB4 (20/528), CUL3 (11/528), PTEN (9/528), ZNF750 (13/528) and NOTCH1 (8/528)." (PMID 36272974, 2022). "Since the effect of FAT1 knockdown on TGF-β1 modulation was seen to begin at the mRNA level, we checked whether FAT1 has a role in regulating miR-663a expression in cancer cells." (PMID 35720420, 2022).
cancer (continued). "These regions contain important cancer-related genes including TRIM28, SEMA3C, NOTCH1, and FAT1." (PMID 34168152, 2021). "Despite the clinicopathologic implication of FAT1 in many malignant tumors, its function in OCSCCs or OSCCs has not been yet clarified." (PMID 34070941, 2021). "As already pointed out, FAT1 is over-expressed in most human CRCs and the 25 amino acid hD8-FAT1 domain recognized by mAb198.3 is exposed on cancer cells and not on healthy human tissues." (PMID 30416985, 2018). "Here, we briefly summarize studies that report an effect of FAT1—negative or positive—on cancer cell migration, as understanding its disparate effects in different cancer types could lead to a greater understanding of how FAT1 affects VSMC migration." (PMID 37371091, 2023). "Thus, our results suggested that FAT1 may possibly promote the translation of TGF-β1 via suppression of miR-663a levels, in turn affecting the immunomodulatory properties of cancer cells." (PMID 35720420, 2022). "Indeed, FAT1, CASP8, CDKN2A, and NOTCH1 mutations were found more frequently in these tumors compared with other HNCs malignancies and other squamous non-HNCs cancers." (PMID 34440249, 2021). "Simultaneously, based on the COSMIC mutation database, no hotspot region was observed for FAT1 mutations in HNSC, so we selected 4 most frequent mutation sites detected in multiple cancers, which may have implications for protein function, to be validated by Sanger sequencing." (PMID 35646625, 2022). "Co-occurring of genetic mutations in cancers with KDM5C alterations were not uncommon in both early-stage and advanced stage cohort and some of them are prevalent driver genes (e.g., LRP2, KMT2C, PBRM1, NOTCH1, FAT1, SETD2, NSD1, etc.), while their clinical significance remained undetermined." (PMID 33953726, 2021). "Therefore, we could rule out that the cancer prevention outcome was not related with lowered colonization in Fat-1 TG mice, even though an in vitro study showed some bacterostatic effects of EPA or DHA." (PMID 27528223, 2016). "FAT atypical cadherin 1 (FAT1) is one of the most mutagenic genes in tumors, and several critical studies have revealed its role in tumors, although no pan-cancer studies are currently available." (PMID 36517565, 2022). "However, it is still possible that other molecular events may control YAP activation in >65% of HNSCC cases that do not exhibit YAP1 or FAT1 genomic alterations, whose elucidation may help reveal new molecular mechanisms controlling the Hippo pathway in cancer." (PMID 34725466, 2021). "Whether or not FAT1 regulates GPC3 expression during human embryonic development and cancers is a question that remains to be explored." (PMID 33878524, 2021). "We have recently reported that frequent FAT1 alterations contribute to YAP activation in HNSCC, however many FAT1 wild type HNSCC cases also exhibit nuclear YAP8, and as such, the mechanism of YAP activation in HNSCC, and other cancer types, may not yet be fully understood." (PMID 34725466, 2021).
infection (8 papers, 2008 to 2023). The state of being infected such as from the introduction of a foreign agent such as serum, vaccine, antigenic substance or organism. "Infection of FAT-1 transgenic mice that are capable of synthesizing n-3 PUFAs from n-6 PUFAs with lymphocytic choriomeningitis virus (LCMV) resulted in significant reduction of anti-viral CD8+ T cell responses." (PMID 31547227, 2019). "However, infection of EPA-supplemented nematodes resulted in up-regulation of fat-1 and significant down-regulation of lipid metabolism genes, including fat genes fat-5, elo-5, elo-7, cyp-29A3, cyp-33C1 and cyp-33E1." (PMID 37672050, 2023). "Notably, T. gondii-induced phosphorylation of AMPK, CaMKKβ, and LKB1 was obviously increased at 18 h after infection in Fat-1-derived macrophages compared to WT macrophages." (PMID 31500218, 2019). "However, fat-1 transgenic mice, which endogenously produce n-3 PUFAs, infected with virulent H37Rv Mtb via the aerosol route, also had increased bacterial loads in the spleen at 4-, 8- and 12-weeks post-infection." (PMID 33995381, 2021). "We often observed modulation of multiple members of the same protein family, increasing the likelihood of biological relevance; for example, six of six γ-protocadherins that are downregulated during infection may be novel NK ligands in addition to protocadherin FAT1." (PMID 24906157, 2014). "Interestingly, protocadherins were also downregulated after infection with HCMV and knockdown of protocadherin FAT1 in target cells led to decreased NK cell degranulation." (PMID 35727847, 2022). "Mutants deficient in different 20-carbon PUFAs, such as elo-1(gk48), elo-1(wa7), fat-1(wa9), fat-4(ok958) and fat-4(wa14) show no defects in their response to infection." (PMID 19023415, 2008).
adenocarcinoma (4 papers, 2016 to 2024). A common cancer characterized by the presence of malignant glandular cells. "The other genes that were much more mutated in SCC (with estimated mutation proportion in SCC and in adenocarcinoma, respectively) were LRP1B (23%, 10%), KMT2D (16%, 7%), FAT1 (15%, 5%), CDKN2A (12%, 2%), NOTCH1 (10%, 3%), and NFE2L2 (10% and 1%)." (PMID 34645806, 2021). "1:1 mounting view of whole stomach of WT – H. pylori group showed moderately-differentiated adenocarcinoma, by which there was significant difference in tumorigenesis between WT and Fat-1 TG mice at 45 weeks after H. pylori infection." (PMID 27528223, 2016). "At present, the genetic characteristics of MiNENs containing adenocarcinoma components have been investigated in the digestive system, and it is suggested that CCNE1 gain and FAT1 loss might promote the tumorigenesis of MiNENs partially through regulating cell cycle G1/S checkpoint signaling." (PMID 38884082, 2024).
cardiovascular disease (3 papers, 2011 to 2022). "These processes may incorporate critical points that are susceptible to therapeutic intervention in cardiovascular disease, yet our understanding of FAT1 in vascular biology is far from complete." (PMID 35647082, 2022). "Although there are no reports concerning correlation between FAT1 and cardiovascular disease, some authors found Fat1 may control vascular smooth muscle cell functions by facilitating migration and limiting proliferation." (PMID 30166997, 2018).
head and neck tumors (3 papers, 2020 to 2025). "In murine models bearing FAT1‐mutant head and neck tumors, LNP‐sgFAT1 demonstrated enhanced antitumor activity when combined with CPI‐613." (PMID 40407216, 2025). "In addition, protein expression levels of FAT1 were determined in a cohort of 109 head and neck tumors and 70 normal head and neck tissue samples in the CPTAC database, consistently, which was upregulated in HNSC tissues (P < 0.0001)." (PMID 35646625, 2022). "Genomic studies of head and neck tumors have shown that although β-catenin is not frequently mutated in HNSCC, its activity is not inhibited by mutations in upstream gene encoding β-catenin, NOTCH1, FAT1, and AJUBA." (PMID 33469547, 2020).
metabolic disorders (3 papers, 2022 to 2025). "Transplantation of Fat-1 BAT reduces high-fat diet-induced metabolic disorders." (PMID 35628137, 2022).
hematological cancer (2 papers, 2022 to 2024). "Inherited FAT1 mutations affect kidney development and have been linked to clinical glomerulotubular nephropathy, while somatic mutations are increasingly recognized in both solid tissue and hematopoietic cancers." (PMID 35647082, 2022). "Similarly, clinical data from the MSK-IMPACT Heme project showed worse survival for FAT1-mutated blood cancer patients and FAT1-mutated ALCL subgroup compared to non-mutated cases, suggesting a general prognostic role of FAT genes in hematological cancer." (PMID 39478125, 2024).
psychiatric disorder (2 papers, 2018 to 2023). A disorder characterized by behavioral and/or psychological abnormalities, often accompanied by physical symptoms. "The present study detects three psychiatric disorder‐relevant genes (CLSTN2, FAT1, and SLC18A1) that have been under positive selection during the human evolution." (PMID 30283697, 2018).
autosomal recessive disease (1 paper, 2023). Autosomal recessive form of disease. "With our study, we provided Moderate or Strong level of evidence for GDR for 11 genes that were not listed in OMIM as having phenotype entity: FBRSL1, AGR2, ACBD6, C1orf127, PAN2, VPS50, KCTD3, NOTCH3 (for autosomal recessive disease), FAT1, NRAP, and SCLT1." (PMID 39669245, 2023).
infectious disease (1 paper, 2019). A disorder directly resulting from the presence and activity of a microbial, viral, or parasitic agent in humans. "Based on previous studies showing that ω3-PUFAs have immunomodulatory properties in various infectious diseases, we examined whether endogenous ω3-PUFAs exhibit host-protective effects against T. gondii infection using Fat-1 transgenic mice and Fat-1-derived primary macrophages." (PMID 31500218, 2019).
FAT1 also shares sentences with these, for which no sentence is quoted: non-small cell lung carcinoma (8 papers); fatty liver (4); Alzheimer disease (2); B-cell acute lymphoblastic leukemia (2); ductal carcinoma in situ (2); dyslipidemia (2); endotoxemia (2); holoprosencephaly (2); Hyperinsulinemia (2); leukoplakia (2); ptosis (2); triple-negative breast carcinoma (2); acute myocardial infarction (1); anemia (1); aortic valve disease (1); arteriosclerosis (1); autoimmune hepatitis (1); bowel cancer (1); brain injury (1); carcinoid tumor (1); carcinoma in situ (1); clear cell renal cell carcinoma (1); colon (1); colorectal adenocarcinoma (1); colorectal tumor (1); diffuse astrocytoma (1); diffuse large B-cell lymphoma (1); endocervical carcinoma (1); focal segmental glomerulosclerosis (1); follicular lymphoma (1).
A further 40 diseases each share a sentence with FAT1 in 1 paper.